HDAC1 (histone deacetylase 1)
Diseases named in the same sentence as HDAC1 in open-access papers (continued):
Sharing a sentence is not in itself a finding about the gene and the disease.
gastric cancer (continued). "HDAC1 were significantly up-regulated in gastric cancer and could promote tumorigenesis and inhibit apoptosis." (PMID 34880761, 2021). "Additionally, HDAC1 expression was negatively correlated with the OS rate of patients with gastrointestinal malignancies, especially gastric cancer." (PMID 28424407, 2017). "Finally, we found that gastrointestinal cancer patients with low HDAC1 expression showed better OS than those with high HDAC1 expression, especially with gastric cancer." (PMID 28424407, 2017). "In addition, we also found that patients with low HDAC1 expression showed better overall survival than those with high HDAC1 expression in gastrointestinal malignancy, especially in gastric cancer (HR = 1.88, 95% CI = 1.14–3.12, P = 0.01)." (PMID 28424407, 2017). "Moreover, the effect of treatment of gastric cancer cells with HDAC inhibitor TSA was similar to that of 5-aza-dC with regard to differential HDAC1 and HDAC2 binding." (PMID 26675260, 2016). "Therefore, MORC2-mediated p21 repression is involved in HDAC1 modification in gastric cancer cell lines." (PMID 26098774, 2015). "High expression of HDAC1/2 was found in gastric carcinoma tissues." (PMID 24896240, 2014). "Sgc-7901 xenograft tumor model showed that Valproic acid (2-propylpentanoic acid, VPA) could inhibit histone deacetylase 1/2(HDAC1/2) activity and induce autophagy in gastric cancer cells, which can further inhibit the HDAC1/PTEN/Akt signaling pathway as well as regulate Bclin-1 and Beclin-2." (PMID 35463631, 2022). "HDAC1 inhibition could suppress the expression of PD-L1 induced by the IFN-γ signal pathway via down-regulating nucleus translocation of JAK2-mediated STAT1 in gastric cancer cells." (PMID 34880761, 2021). "Similarly, MORC2 represses p21 in gastric cancer cells by recruiting HDAC1 to the p21 promoter." (PMID 29329290, 2018). "HDAC1 and G9a overexpression inhibits the nuclear localization and RUNX3 expression under hypoxic condition in gastric cancer cells." (PMID 38683453, 2024). "Univariate Cox regression analysis revealed that HDAC1, HDAC5, HDAC8, SIRT3, and SIRT6 were significant predictors of gastric cancer." (PMID 37649598, 2023). "HDAC-1 overexpression has been connected with advanced disease stage in cases of mobile tongue SCC, NSCLC, primary or recurrent gastric cancer and intrahepatic cholangiocarcinoma." (PMID 33799478, 2021). "Prominent validated targets include CDK6, MYC, CCNE2, MET and GMNN and we furthermore validated the regulation of HDAC1 and SIRT1 also in gastric cancer cells." (PMID 21418558, 2011). "On western blotting analysis, OCUM-2MD3 cells showed high levels of HDAC1 and HDAC2 compared with the other human gastric cancer cell lines." (PMID 21080974, 2010). "HDAC1 and HDAC2 expression were evaluated by western blotting in OCUM-2MD3 cells and other gastric cancer cell lines (TMK-1, MKN-28)." (PMID 21080974, 2010). "Both HDAC1 and HDAC2 play important roles in the aggressiveness and carcinogenesis of gastric cancer." (PMID 21080974, 2010). "We also ruled out the involvement of HDAC1/2 in the Honokiol-induced effects on gastric cancer cells." (PMID 34973135, 2023). "For example, HDAC1 is involved in the promotion of gastric cancer cell proliferation, possibly by upregulating the expression of lncRNAs BC01600 and AF116637 in the tissues of patients with gastric cancer." (PMID 35965507, 2022). "Additionally, histone deacetylase 1 (HDAC1) is an upstream factor of TRIP13, which could target the TRIP13 promoter region to promote the proliferation, migration, and invasion of gastric cancer cells." (PMID 39187490, 2024).
gastric cancer (continued). "Moreover, HDAC1 and HDAC2 have been reported to be up-regulated in gastric cancer." (PMID 26036259, 2015). "Therefore, expression of HDAC1 and -2 are not helpful to predict response to treatment or survival in gastric cancer patients treated with neoadjuvant therapy, but HDAC1 expression may be beneficial for risk stratification in patients with disease that responds to therapy." (PMID 39497715, 2024).
pancreatic cancer (40 papers, 2009 to 2026). "The current study found that HDAC1 is closely associated with the development and progression of pancreatic cancer." (PMID 37880235, 2023). "In addition, HDAC1 is linked to unfavorable prognosis and resistance to chemotherapy in cases of pancreatic cancer." (PMID 38933262, 2024). "We previously demonstrated that overexpression of HDAC1 contributes to multidrug resistance in pancreatic cancer cells." (PMID 37996815, 2023). "Pancreatic cancer cells proliferate and migrate more readily because of HDAC1 and HDAC2-mediated inhibition of E-cadherin expression in tumor cells." (PMID 36902253, 2023). "HIF-1α plays a vital role as a transcriptional regulator of hypoxia-induced EMT, and a significant correlation exists between HIF-1α and HDAC1 expression in pancreatic cancer." (PMID 36902253, 2023). "High levels of HDAC1 and HDAC2 expression are linked to distant pancreatic cancer transitions, and both proteins enhance tumor invasiveness." (PMID 36902253, 2023). "A main mechanism is that Snail can recruit HDAC1/2 and Sin3A complexes into the E‐cadherin promoter, then down‐regulate the expression of E‐cadherin, and promote the metastasis of pancreatic cancer." (PMID 33325150, 2021). "Contrariwise, high levels of HDAC-1 expression have been connected with favorable prognosis in invasive breast and pancreatic carcinoma." (PMID 33799478, 2021). "In pancreatic cancer cells, HDAC1 is recruited to the CDH1 promoter, resulting in deacetylation of histone 3 and histone 4 proteins in the nucleus and depletion in E-cadherin, which consequently helps in the epithelial–mesenchymal transition (EMT)." (PMID 32210140, 2020). "The overexpression of HDAC1 and mutant KRAS were known to cause proliferation of pancreatic cancer cells, and therefore silencing the two genes was used as an anti-cancer strategy in this study." (PMID 32038249, 2019). "In human pancreatic cancers, 56% of pancreatic cancers show positive immunehistochemical staining for HDAC1, and the co-expression of HDAC1 and hypoxia-inducible factor-1α (HIF-1α) markedly correlates with poor prognosis." (PMID 24281216, 2010). "The study showed that the modified GO could simultaneously deliver siRNA of the HDAC1 and KRas1 genes to the pancreatic cancer cell MIA PaCa-2 with high selectivity, as well as inhibit the expression of HDAC1 and Kras genes." (PMID 40142970, 2025). "HDAC1 inhibitors have demonstrated efficacy in the treatment of several cancers, including gastric, breast, colorectal, prostate, colon, lung, ovarian, and pancreatic cancers, as well as in managing inflammation, with minimal associated toxic effects." (PMID 39075515, 2024). "The authors demonstrated the potential of multi-functionalized monolayer GO as a gene delivery platform to co-deliver HDAC1 and K-Ras siRNAs (small interfering RNAs targeting the HDAC1 gene and the G12C mutant K-Ras gene, respectively) to specifically target pancreatic cancer cells." (PMID 38068178, 2023). "In addition, class I HDACs promote the epithelial-to-mesenchymal transition (EMT) of pancreatic tumor cells via the Snail/HDAC1/HDAC2 complex, which subsequently suppresses E-Cadherin expression." (PMID 35327319, 2022). "Our previous study also demonstrated miR-548an could be transcriptionally downregulated by HIF1α/HDAC1, further suppressing tumorigenesis of pancreatic cancer." (PMID 34930270, 2021). "HIF-1α could inhibit E-cadherin expression via recruiting metastasis-associated protein 2 (MTA2)/HDAC1 complex to bind to E-cadherin promoter, inducing EMT in pancreatic cancer cells." (PMID 32587480, 2020). "After PaCa-2 pancreatic cancer cells were treated with synthesized GO sheet, the successful delivery of siRNA and gene silencing were confirmed by analysing the mRNA level of Kras and HDAC1 with RT-PCR and the protein levels with western blots." (PMID 32038249, 2019).
pancreatic cancer (continued). "In addition to the HDAC1/HDAC2-dependent transcriptional regulation of MYC in pancreatic carcinoma cells, our data collected with RGFP966 suggest that HDAC3 supports the expression of MYC in leukemic cells." (PMID 31561534, 2019). "Moreover, snail mediates E-cadherin repression by the recruitment of the HDAC1/2 complex and E-cadherin is suppressed by a snail/HDAC1/HDAC2 complex to regulate metastasis of pancreatic cancer." (PMID 26336990, 2015). "We also performed a Kaplan-Meier survival analysis, which revealed that the higher expression of HDAC1, HDAC2, HDAC7, and HDAC9 led to poor overall survival in pancreatic cancer patients." (PMID 39123441, 2024). "In pancreatic cancer, SOX6 downregulates TWIST1 by recruiting HDAC1 to the TWIST1 promoter, which inhibits pancreatic cancer metastasis." (PMID 38331879, 2024). "Snail mediates the recruitment of the Sin3A/HDAC1/2 complex into the CDH1 promoter, where it inhibits CDH1 expression and enhances pancreatic cancer metastasis." (PMID 35144601, 2022). "The recruitment of HDAC1 and HDAC2 by the transcriptional repressor ZEB1 results in CDH1 down regulation in pancreatic cancer." (PMID 35144601, 2022). "In pancreatic cancer, HIF-1α recruits histone deacetylase 1 (HDAC1) to the promoter of miR-548an, which transcriptionally suppresses miR-548an expression and subsequently upregulates vimentin, which facilitates pancreatic tumorigenesis." (PMID 34884541, 2021). "ZEB1 regulates the recruitment of HDAC1 and HDAC2 to the CHD1 promoter in human pancreatic cancer cells." (PMID 32210140, 2020). "Moreover, ZEB1 can also recruit NuRD complex, which contains HDAC1/2, to promote the EMT and tumor progression in pancreatic cancer and lung cancer." (PMID 35601657, 2022). "Additionally, ZEB1 can down-regulate E-cadherin expression via recruiting histone deacetylases HDAC1 and HDAC2 in pancreatic cancer." (PMID 26036631, 2015). "HDAC1 and HDAC7 are increased in human pancreatic tumors compared to normal tissue." (PMID 23696899, 2013). "Depletion of HDAC2, but not HDAC1, in the pancreatic cancer cell lines MiaPaCa2 and Panc1 resulted in a marked sensitization towards the tumor necrosis factor-related apoptosis-inducing ligand (TRAIL)." (PMID 20398369, 2010). "Notably, HDAC1-positive tumors have been correlated with pancreatic cancer patients’ low survival compared to HDAC1-negative tumors." (PMID 39123441, 2024). "For example, Snail has been found to form protein complex with HDAC1 and HDAC2 at the promoter of E‐cadherin, leading to the deacetylation and consequent repression of E‐cadherin, which results in the EMT and migration of breast cancer, pancreatic cancer, and nasopharyngeal cancer." (PMID 35601657, 2022). "The elevated expression levels of HDAC-1, −2, −4 and −6 in pancreatic adenocarcinoma may reinforce the therapeutic utility of HDAC targeting in pancreatic cancer chemoprevention, taking into consideration the anti-cancer properties of HDACIs in cell proliferation, differentiation and apoptosis." (PMID 26502922, 2015).
melanoma (32 papers, 2007 to 2025). A malignant, usually aggressive tumor composed of atypical, neoplastic melanocytes. "However, neither HP1α nor HP1γ showed appreciable changes in chromatin association after HDAC1 induction in melanoma cells." (PMID 17578512, 2007). "Finally, this model accounts for the results described herein, namely, overexpression of HDAC1 can overcome the loss of p16INK4a and induce senescence in human melanoma cells." (PMID 17578512, 2007). "In melanoma, PD-L1 seems to be directly controlled primarily by class I HDACs (HDAC1, HDAC2, HDAC3, HDAC8)." (PMID 38672128, 2024). "One such compound which has been reported to target the CoREST complex is Corin, and its mechanism of dual targeting of LSD1 and HDAC1 in the CoREST complex seems to contribute to its enhanced cellular pharmacology in melanoma." (PMID 36595522, 2023). "The inhibition of HDAC1/2/3 by valproate or entinostat sensitized melanoma cells to the chemotherapeutic agent temozolomide and impeded melanoma xenografts outgrowth." (PMID 35409020, 2022). "For example, HDAC1 somatic mutations have been found in 8.3% of dedifferentiated liposarcoma and HDAC4 homozygous deletions are found in 4% of melanoma." (PMID 32158695, 2020). "Melanomas contain high levels of HDAC-1, 2 and melanoma cells have been shown to overexpress HDAC-1, -2, -3, compared to non-malignant cells." (PMID 30719233, 2019). "In melanoma cells knock down of [HDAC6 + HDAC2] or [HDAC6 + HDAC10] significantly enhanced pazopanib lethality whereas knock down of [HDAC6 + HDAC1] or [HDAC6 + HDAC3] were less effective." (PMID 29137331, 2017). "MITF-M expression in melanocytes and melanoma cells was shown to be suppressed by multiple inhibitors of HDAC1." (PMID 26824319, 2016). "Our study has shown for the first time that PN can markedly decrease the HDAC1 level also in melanoma." (PMID 26824319, 2016). "Here, we demonstrate that the combination of ectopic p73 expression after knockdown of HDAC1 synergistically generates enhanced cytotoxicity in metastatic melanoma cells." (PMID 25071017, 2014). "As previous reports demonstrated increased apoptosis after HDAC1 inhibition or p73 overexpression in melanoma cells, the capability of our oncolytic viruses to induce apoptosis was analyzed." (PMID 25071017, 2014). "In melanoma cells infected with viruses containing shHDAC1, the histone deacetylase level was significantly reduced via inhibiton of the HDAC1 mRNA by the specific shRNA." (PMID 25071017, 2014). "In conclusion, the GST pull-down assays in normal senescent melanocytes support the findings using the HDAC1-inducible model in melanoma cells." (PMID 17578512, 2007). "Similarly, overexpression of HDAC1 was observed in multidrug resistant neuroblastoma cell lines and increased resistance of melanoma cells to sodium butyrate, whereas HDAC1 siRNA knockdown sensitized neuroblastoma cells to etoposide." (PMID 38369747, 2024). "The target predictions indicate that TPPS may interact with four melanoma targets: telomerase reverse transcriptase, C-X-C chemokine receptor type 4, histone deacetylase 1, and galectin-3." (PMID 36365208, 2022). "Our findings that PN efficiently reduces the levels of MITF-M and HDAC1 in melanoma cells, especially when combined with the previous results on its inhibitory effect on NF-κB activity, might have important implications for the clinics." (PMID 26824319, 2016). "PN-induced inhibition of HDAC1 seems to be a common mechanism for all melanomas." (PMID 26824319, 2016).
melanoma (continued). "We further confirmed the highest therapeutic efficacy of the oncolytic virus that co-expresses HDAC1 shRNA and p73 in a mouse xenograft model by treating aggressively growing melanomas with a low virus dose of 3 × 108 PFU separated over three consecutive injections of 1 × 108 each." (PMID 25071017, 2014). "To address chemoresistance of malignant melanoma due to defects in death pathways, we aimed at apoptosis reactivation by concomitant expression of two effectors of apoptosis: p73 and an shRNA to suppress HDAC1 to reopen apoptotic routes." (PMID 25071017, 2014). "In addition, depsipeptide, a potent histone deacetylase 1/2 inhibitor, enhances effector T cell function by up-regulating Perforin expression in melanoma-specific, antigen-stimulated effector T cells as well as FAS expression on B16-F10 melanoma to induce tumor cell apoptosis in vitro and in vivo." (PMID 32560120, 2020). "Moreover, inhibition of HDAC1 was reported as the mechanism of MITF downregulation in melanoma." (PMID 26824319, 2016). "In melanoma cells, TBX2 recruits HDAC1 to the p21 promoter, silencing its expression and enabling continued proliferation—even in the absence of CDKN2A, a well-known tumor suppressor frequently mutated in melanoma." (PMID 40723431, 2025). "Consistent with previous findings, FK228, a potent HDAC1 and HDAC2 inhibitor, significantly reduced the HIF-1α protein levels in melanoma." (PMID 36831463, 2023). "For example, MS-275, which inhibits class I HDACs, including HDAC1, decreases RAD51 expression and blocks HR in melanoma cells." (PMID 30382096, 2018). "Expression levels of HDAC1 and HDAC2 are higher in melanoma cells resistant to anti-cancer drugs than those in melanoma cells sensitive to anti-cancer drugs." (PMID 30583572, 2018). "Our data suggest that parthenolide can be developed as a drug used in combination therapy against melanoma when simultaneous inhibition of MITF-M, NF-κB and HDAC1 is needed." (PMID 26824319, 2016). "We have recently described corin, a potent and specific dual-warhead inhibitor of the CoREST complex targeting HDAC1/2 and LSD1, that demonstrates growth inhibition in melanoma, cutaneous squamous cell carcinoma, breast cancers, and diffuse intrinsic pontine glioma." (PMID 38300709, 2024). "Because, as by protein profiles, several HDACs (HDAC-1, −2, −5, −7, and −8) appeared to be increased in FKBP51-silenced melanoma cell, we used trichostatin A (TSA) to investigate whether this agent modulated the effect of FKBP51 silencing on DR5 expression." (PMID 34589486, 2021). "HDAC1 cleavage was also observed in other three melanoma populations treated with 20 μM PN for 4 hours (not shown)." (PMID 26824319, 2016). "As PN can inhibit HDAC1 in breast and colon carcinoma cells, we hypothesized that MITF-M level might be also diminished by PN in melanoma cells." (PMID 26824319, 2016). "Similar results were observed for HDAC1 and HDAC3, suggesting that some HDACs may function as melanoma suppressors." (PMID 26747087, 2016). "For example, inhibition of the class I HDAC1, HDAC2 and/or HDAC3 led to acetylation of the PD-L1 and PD-L2 promotors, which augmented up-regulation of PD-L1/L2 protein and RNA transcription in melanoma patients, in melanoma cell lines and in a syngeneic mouse model of melanoma." (PMID 29843754, 2018). "Thus, HDAC2 but not HDAC1 seems to be the critical HDAC that influences the BRN3A expression in melanocytes and melanoma cells with low endogenous mRNA expression of BRN3A." (PMID 35055045, 2022).